S100A8 (S100 calcium binding protein A8)
Diseases named in the same sentence as S100A8 in open-access papers (continued):
Sharing a sentence is not in itself a finding about the gene and the disease.
cancer (continued). "Moreover, ALCAM-specific CAR-T cells can efficiently lyse CRC cells and show powerful cytotoxicity against CRC stem cells, demonstrating a feasible approach for reconstructing CAR-T cells with S100A8/A9 and its receptors for cancer therapy." (PMID 37701037, 2023). "To understand the molecular interaction between rosemary compounds (CA and RA) and a protein that is involved in cancer and inflammation, S100A8, we have performed a series of molecular docking analyses using the available three-dimensional structures (PDBID: 1IRJ, 1MR8, and 4GGF)." (PMID 38202397, 2023). "S100A8/A9, a heterodimer protein mainly generated by neutrophils, triggers many signal transduction pathways to mediate microtubule constitution and pathogen defense, as well as intricate procedures of cancer growth, metastasis, drug resistance, and prognosis." (PMID 37701037, 2023). "To date, S100A8 expression or overexpression of TLR4 has been observed in various cancers." (PMID 36932197, 2023). "Thus, incorporating S100A8/A9 as a supplementary biomarker will aid the early detection and timely treatment of cancers." (PMID 37701037, 2023). "believed that monocytes and macrophages in the metastatic liver microenvironment could induce the expression of S100A8 in cancer cells." (PMID 37124724, 2023). "S100A8/A9 released by cancer cells and tissues interacts with Toll‐like receptor 4 and Receptor for Advanced Glycation End (RAGE) products to direct chemotaxis of myeloid cells and induces proinflammatory responses and/or immune suppressions by activating JAK–STAT, NF‐κB, and MAPK pathways." (PMID 36967480, 2023). "Indeed, iASPP-deficient cells increased expression of inflammatory cytokines S100a8 and S100a9, which are also expressed by apoptotic cancer cells and can promote metastasis." (PMID 36746936, 2023). "The role of S100A8/A9 in cancer progression needs further investigation." (PMID 38093319, 2023). "Furthermore, the percentage of weight loss within 6 months before cancer diagnosis in PC patients positively correlated with serum levels of S100A8 (r = 0.33, P < 0.001), S100A9 (r = 0.30, P < 0.001), and S100A8/A9 (r = 0.24, P = 0.004)." (PMID 37280516, 2023). "In addition, many studies have shown that Toll-like receptor 4 (TLR4), NF-κB, matrix metalloprotease-2 (MMP-2), and other proteins also participate in S100A8/A9-mediated cancer cell migration and invasion through different transduction pathways." (PMID 37701037, 2023). "These MDSCs engender cancer cell chemoresistance and metastatic propagation through S100A8." (PMID 36241629, 2022). "This study provided more information about the role of S100A8 in cancer immunotherapy." (PMID 35646116, 2022). "However, S100A9, together with S100A8, were the two genes with the most variable expression pattern among cancer cells." (PMID 35411077, 2022). "CGNL1 and S100A8 are down-regulated in most cancers and up-regulated in a few cancers." (PMID 36626444, 2022). "The second point to consider is that HRG was downregulated in our patients with brain-metastatic lung cancer, which would lead to the circumstance that S100A8/A9 was dominant in the cancer milieu at the onset site as well as in the cancer premetastatic environments in the remote organs." (PMID 36142212, 2022). "Furthermore, the bioinformatics research revealed some interesting details concerning S100A8's function in cancer." (PMID 35646116, 2022). "Stat3-mediated upregulation of S100A8/9 promotes accumulation of MDSCs in cancer." (PMID 34976216, 2022). "Together, these results suggest that intranasal S100A8 treatment contributes to the reprogramming of the lung microenvironment to reduce ROS and NO and creates a potentially more favorable microenvironment for supporting anti-cancer lymphocytes." (PMID 35655772, 2022). "S100A8 has increased in prominence as a target for anticancer treatment research because of its essential function in triggering inflammatory pathways that aid in cancer spread." (PMID 35646116, 2022).
cancer (continued). "Together, these observations suggest that S100A8 may promote anti-oxidative effects in the lungs, thereby creating a favourable anti-cancer redox microenvironment." (PMID 35655772, 2022). "Moreover, we have reported an unusual role of S100A8/A9 in the metastasis of lung-tropic cancer—namely, binding to the cell surface S100 soil sensor receptors (SSSRs)." (PMID 36142212, 2022). "S100A8 can directly affect proliferation and viability of some cancer cell types." (PMID 35655772, 2022). "Therefore, in addition to cancer disease, it is likely that S100A8/TLR4/MD-2 axis can be a promising therapeutic target against other inflammation-associated diseases." (PMID 35780158, 2022). "Thus, an elevated level of S100A8/A9 is a critical danger signal triggering cancer metastasis via certain molecular mechanisms." (PMID 36142212, 2022). "However, we previously showed that a neutralizing anti-S100A8/A9 antibody conferred protection against both cancer metastasis and inflammatory responses." (PMID 36142212, 2022). "CCL22 is found in a broad range of human cancers with potent pro-tumoral functions, while S100A8 and S100A9 are expressed by MDSCs in human CRC patients, are associated with the recruitment and immunosuppressive functions of MDSCs, and correlate with advanced CRC." (PMID 35658010, 2022). "Intriguingly, MDSCs are also implicated in MET in cancer cells and during the formation of premetastatic niches; MDSCs reach the niche before the cancer cells and promote their seeding by secreting immunosuppressive factors, including S100A8/A9, FGF-β, IL-10, and IL-4." (PMID 34576042, 2021). "S100A8 have been shown to be overexpressed in aggressive phenotype and in patients with low overall survival, suggesting that regulation of S100A8 gene expression is a mechanism that participates in cancer cells control." (PMID 33801279, 2021). "Downregulation of S100A8 enhances sensitivity of cancer cells to DOX chemotherapy." (PMID 33187385, 2020). "Despite a relatively short DSS administration period, WOL intervention improved the expression levels of cancer-related proteins in the colon (Anxa3 and Co3) as well as oncogenic hepatic genes (Saa1, Jun and S100a8) as observed in the DSSWOL mice as compared to the DSS group." (PMID 32258419, 2020). "Some investigations indicate S100A8/A9 upregulation in cancer." (PMID 33117687, 2020). "S100A8 acts as a ligand for RAGE to promote cell migration in cancers and PCOS conditions." (PMID 32478041, 2020). "For example, TAMs-secreted CXCL1 could recruit myeloid-derived suppressor cells (MDSCs) into the TME, which secreted chemokines including S100A8/9 that enhanced cancer cell survival, chemoresistance, metastasis, and pre-metastatic niche formation." (PMID 32300100, 2020). "However, little is known about the mechanism that regulates S100A8/S100A9 co-expression in cancer cells." (PMID 31208368, 2019). "However, studies evaluating the prognostic role of S100A8 protein expression in cancer cells are still rare." (PMID 30456203, 2018). "However, studies strongly suggest that S100A8 is expressed by cancer cells as well as by infiltrating immune and myeloid cells." (PMID 30456203, 2018). "These discoveries motivate researchers to explore whether S100A8/A9 could be used as a biomarker or therapeutic target in diseases beyond inflammation and cancer." (PMID 29942307, 2018). "This mutational landscape might influence cancer cells response to EGF, Transforming Growth Factor β1 (TGFβ1) and stromal inflammatory calcium binding proteins S100A8/A9." (PMID 27655713, 2016). "The expression of S100A8/A9 is also intimately linked with SMAD4 status: it is prevalent in stromal cells when cancer cells express SMAD4, whereas in SMAD4 homozygous deletion cancer cells independently acquire the ability to express S100A8/A9." (PMID 27655713, 2016). "Increased expression of S100A8/A9 has also been recently identified in various human cancers." (PMID 26799323, 2016).
cancer (continued). "Reduced S100A8/A9 expression appears to promote the HNSCC phenotype, since loss of differentiation and cell-to-cell contact growth inhibition can dysregulate cell cycle progression and increase carcinoma growth." (PMID 26883112, 2016). "In separate experiments, genes highly upregulated in HNSCC were further interrogated for their regulation by S100A8/A9 by ectopic overexpression in S100A8/A9-negative carcinoma cells and by knockdown of endogenous S100A8/A9 expression in HNSCC cells using short hairpin RNA (shRNA) interference." (PMID 26883112, 2016). "To confirm our hypothesis that the inflammation seen in fibrotic NASH patients might lead the way to cancer, we investigated the level of the two calgranulins, S100A8 and S100A9, in the serum of patients affected by NASH." (PMID 26273651, 2015). "However, under pathological conditions like inflammation and cancer, an increased expression of S100A8 is seen in epithelial cells." (PMID 25789858, 2015). "Overall, our findings support the hypothesis that S100A8, S100A9 and NT-S100A8 are Janus-faced molecules that can have pro- and anti-cancer effects, depending on the cellular context." (PMID 24670043, 2014). "In addition to inflammatory conditions, overexpression of S100A8/A9 has also been observed in various types of cancer including stomach, prostate, breast, skin, pancreas, liver, lung, bladder, colon, and esophageal cancers." (PMID 25371673, 2014). "S100A8/A9 (or calprotectin) may therefore function as a growth suppressor in carcinoma cells and reduced expression may serve as a signal for aggressive growth." (PMID 23874958, 2013). "S100A8/A9-dependent reduction in expression of cyclin B1 and hyperphosphorylation of p-Cdc2 (Thr14/Tyr15) shown in this study are consistent with Cdc2 inactivation and G2/M checkpoint arrest as commonly reported in carcinomas." (PMID 23874958, 2013). "Reduction in S100A8/A9 in carcinomas (in HNSSC for example) may lead to a diminished PP2A phosphatase activity and increased growth and tumorigenesis." (PMID 23874958, 2013). "Recent clinical and experimental data have suggested that changes in the expression and/or function of the S100A8 protein may represent a key step during cancer development." (PMID 22139384, 2012). "While most studies showed that S100A8/A9 is overexpressed in various types of cancers, these proteins might also be underexpressed in some other cancers." (PMID 22685372, 2012). "S100A8 and S100A9 play pathogenic roles in cancer progression in a concentration-dependent manner." (PMID 22489132, 2012). "More recently, the p38 MAPK signalling cascade was also shown to play a pivotal role in cancer cell migration, and could be stimulated by S100A8." (PMID 23157946, 2012). "To begin to address mechanisms that might be responsible for this HV-68-exacerbated cancer, we questioned whether virus-induced increases in S100A8/S100A9 levels might induce increased MDSCs in vivo." (PMID 22946998, 2012). "In addition, as shown in, the pathway “cell cycle” was placed at the very top, indicating that the largest number of S100A8/A9-upregulated genes mapped to the “cell cycle” category (green arrows and circles), which is essential to the acceleration of cancer growth." (PMID 40924339, 2025). "Furthermore, S100A8 could be considered a novel target for drug design and a biomarker for the diagnosis and prognosis of cancer." (PMID 38607060, 2024). "Notably, S100A8/A9 has the potential to promote cancer progression." (PMID 38093319, 2023). "The main suppliers of S100A8/A9 are inflammatory cells including neutrophils, monocytes, macrophages, and myeloid-derived suppressor cells (MDSCs) that gather in a cancer in situ microenvironment and in a premetastatic microenvironment in organs that are favored by cancer, such as the lungs." (PMID 37091157, 2023). "Similarly, the protein S100A8 is overexpressed in many common cancers, particularly in BC." (PMID 37450087, 2023).
cancer (continued). "Finally, stratifying patients regarding their HPV/S100A8/S100A9/CD15/CD147 profile may help identify patients with progressing cancer and tailor immunotherapeutic treatment strategies." (PMID 36303837, 2022). "As a sensitive indication, S100A8 may be an important new target or biomarker for cancer detection." (PMID 35646116, 2022). "More recent investigations targeting the role of neutrophil subsets during carcinogenesis suggested that distinct subsets, of naturally occurring and TME-induced subsets, could display an increased capacity to support cancer progression and to upregulate S100A8/A9 expression." (PMID 36303837, 2022). "We next examined whether S100A8 treatment increased survival of mice with LLC cancers." (PMID 35655772, 2022). "Importantly, S100A8 treatment significantly increased activities of these enzymes in lungs with LLC cancers (SOD: 117.1 ± 22.3 to 209.2 ± 22.0 nmol/min/mg protein, p < 0.05; TXN reductase: 6.6 ± 1.9 to 19.3 ± 3.9 nmol/min/mg protein, p < 0.05) to control levels." (PMID 35655772, 2022). "Immune activation by S100A8/A9 may reshape the architecture of cancer-immune ecosystem." (PMID 35440136, 2022). "In addition, S100A8/9+ myeloid cells could promote angiogenesis and exacerbate cancer through the S100a8/S100a9–Emmprin–Vegfa axis." (PMID 36420271, 2022). "Similarly, S100A8/A9 attracts cancer cells in the lung in prostate cancer murine models." (PMID 33567747, 2021). "Furthermore, high levels of S100A8 have been found in some diseases, especially in cancer." (PMID 27462864, 2016). "Intracellular S100A8/A9, therefore, may reflect the cancer phenotype." (PMID 26883112, 2016). "The basis for lineage-dependent expression of S100A8/A9 in health and cancer is unknown." (PMID 26883112, 2016). "S100A8 and S100A9 were also found to be overexpressed in tears and saliva collected from patients with forms of cancer, but to a much greater extent (∼10‐fold enrichment) than observed in this study." (PMID 40963435, 2026). "For example, S100A8 and S100A9 activate mitogen-activated protein kinases(MAPK) and nuclear factor-kappaB(NF-κB) signaling, promoting migration and inflammation in cancer cells." (PMID 41404073, 2025). "Recent studies have demonstrated that S100A8 and S100A9 can stimulate the proliferation, migration and invasion of most cancer types 25-27." (PMID 39895787, 2025). "The heterodimer S100A8/S100A9, known as calprotectin, is involved in the immune system, but altered expression of S100 family members is also found in cancers." (PMID 41155408, 2025). "Previous studies have reported that S100A8/A9 increases the expression levels of IL-1β and CCL2 through p38 MAPK/JNK/AP-1 signaling in cancer cells 17-21." (PMID 40860162, 2025). "The expression of S100A8 and S100A9 is tissue- and cell-specific and is changeably enhanced in various cancer types and inflammation-related diseases." (PMID 39895787, 2025). "The known calcium-binding proteins (CALML5, S100A8, S100A14) modulate cancer therapeutics and survival." (PMID 38653992, 2024). "For instance, B2M, SLPI, BST2, GAPDH, S100A8, S100A9, and HMGB1, despite their beneficial roles in various infections, they contribute to cancer cell proliferation, invasiveness, reduced survival, and increased disease severity across different cancers." (PMID 38589404, 2024). "S100 proteins, particularly S100A4, S100A7, and the S100A8/S100A9 heterodimer, are involved in cancer progression, inflammation, and metastasis through their interaction with RAGE." (PMID 39830522, 2024). "Research from both the Gabrilovich lab and Ostrand-Rosenberg lab has identified S100A8 and S100A9 as factors which contribute to differentiating immature myeloid cells to become MDSCs and the accumulation of these cells during cancer progression." (PMID 39497822, 2024).
cancer (continued). "It is worth mentioning that HBA1, S100A8 and S100A9 play important roles in mediating drug resistance in cancer cells, which also provides insights into the mechanism of drug resistance in AML." (PMID 39583114, 2024). "The extracellular form of S100A8/S100A9 functions by modulating cellular oxidative metabolism and facilitating inflammation-to-cancer progression." (PMID 38817853, 2024). "An accumulation of evidence suggests that S100A8/A9 can produce an immunosuppressive TME7,14, potentially contributing to poor outcomes in cancer patients." (PMID 38378783, 2024). "Among the S100 family proteins, S100A8/A9, a heterodimer composed of S100A8 and S100A9, is a notable factor that induces inflammation-mediated cancer metastasis when present at elevated levels in the extracellular environment." (PMID 39570532, 2024). "A role of S100A8, S100A9 or heterodimer S100A8/A9 in the development and function of suppressive MDSCs in cancer was discovered and reported in 2008 by two separate groups." (PMID 39497822, 2024). "The chemotherapeutic drugs induced cancer cells to release more CXCL1 in the TME, leading to the recruitment of MDSCs into tumors and increased S100A8/9 secretion, ultimately increasing cancer cell survival following chemotherapy." (PMID 39394189, 2024). "Double immunofluorescence staining showed that GSDMB+ immune cells in cancer stroma were mostly CD68+ cells and S100A8+ cells." (PMID 38711020, 2024). "S100A8/A9, a heterodimer complex of S100A8 and S100A9, is an attractive molecule in this context because it becomes closely involved in cancer metastasis upon its abundant expression in the extracellular space." (PMID 36910659, 2023). "Cancer-promoting genes including MMP9, S100A8, S100A9, PORK2, and TGF-β1 were identified as high-expression DEGs in NE-1." (PMID 37333017, 2023). "S100A8 also significantly reduced protein levels of IL-6, IL-1β and IL-12β in BALF from mice with LLC cancers (p < 0.05)." (PMID 35655772, 2022). "We found that S100A8 significantly lowered expression of cytokine genes and proteins that promote expansion and activation of MDSC in lungs and BALF from cancer-bearing mice." (PMID 35655772, 2022). "One of these proteins, extracellular S100A4, has been shown to play unusual roles in cancer progression that are very similar to the roles of HMGB1 and S100A8/A9." (PMID 36142212, 2022). "Our findings can contribute to the identification of a relationship between S100A8 expression and immunological TME to further elucidate their possible function in cancer genesis and progression and thus provide immuno-based anticancer therapy." (PMID 35646116, 2022). "S100A8 and S100A9 are constitutively expressed in neutrophils, MDSC and other cell types that promote progression of cancer." (PMID 35655772, 2022). "S100A8 and S100A9 are highly expressed in MDSC and are reported to regulate MDSC activity to promote immunosuppression in cancer." (PMID 35655772, 2022). "The high expression of S100A8 and S100A9 is discussed as an unfavorable prognostic factor for cancer patients." (PMID 36552040, 2022). "IL-10 concentrations in BALF from mice with or without LLC cancers were similar, although IL-10 mRNA expression increased by 80- to 150-fold in response to S100A8 and/or growing LLC cancers." (PMID 35655772, 2022). "A further study indicates that suppression of S100A8 and S100A9 in cancer cells using short hairpin RNA significantly diminished migration and invasion in culture." (PMID 33801279, 2021). "S100A8 and TFDP2 were identified as new gene markers of macrophages and were significantly different between cancer and precancerous stages." (PMID 34745098, 2021). "By analyzing the shared immune features of primary cancers and lymphatic metastases, we unraveled the prognostic value and joint utility of two DEGs, CORO1A and S100A8." (PMID 34337026, 2021). "Of these, S100A8, CLEC10A, and TFDP2 exhibited significantly different expression profiles between cancer and precancerous stages." (PMID 34745098, 2021).